APC (APC regulator of Wnt signaling pathway)
Diseases named in the same sentence as APC in open-access papers (continued):
Sharing a sentence is not in itself a finding about the gene and the disease.
colorectal cancer (continued). "Mutated APC has been observed initially in patients with colorectal cancer." (PMID 36421339, 2022). "Moreover, somatic APC mutations are found in more than 80% of colorectal cancers, but only approximately 5% of colorectal cancers harbor CTNNB1 mutation." (PMID 36428715, 2022). "Lately, reports have stated that in colorectal cancer with classical APC gene mutation, the protein stability of Axin could be enhanced by inhibiting the activity of TNKS1, which further induces β-catenin degradation and Wnt signaling pathway inhibition." (PMID 35450028, 2022). "Recently, PTPRK-RSPO3 (P:R) fusion also contributes to the activation of WNT signaling and causes colorectal cancer, and this mutation is mutually exclusive with the APC mutation and is recognized as another important mutation contributing to the development of colorectal cancer." (PMID 36129915, 2022). "The mutations in β-catenin/Wnt or truncation mutation on adenomatous polyposis coli protein (APC) can induce the over activation of the Wnt/β-catenin signaling pathway, which further promotes the development of colorectal carcinoma, gastric carcinoma, and hepatoma." (PMID 35450028, 2022). "Mutations and truncations in APC, resulting in loss of APC function and hence elevated β-catenin levels and upregulation of Wnt signalling, are associated with numerous cancers including colorectal carcinomas." (PMID 35755812, 2022). "TNKSi-responsiveness in colorectal cancer has been shown to depend on the APC mutation genotype." (PMID 34337362, 2021). "Similarly, while APC is a classical TSG in colorectal cancers, frequently harboring truncating variants, here we also found that APC is a missense mutational cancer gene in ovarian carcinoma and lung squamous cell carcinoma." (PMID 34313788, 2021). "Notably, genetic analyses identified mutational hotspots in the adenomatous polyposis coli (APC) gene in patients with colorectal cancer (CRC)." (PMID 33085215, 2021). "Mutations in the APC gene are responsible for approximately 1% of all colorectal cancer cases." (PMID 34552611, 2021). "Interestingly, rutin targets, especially APC, are also associated with other kinds of cancers such as endometrial, gastric, and colorectal cancers." (PMID 34083561, 2021). "Finally, we tested in a colorectal cancer cell line with an APC mutation if Wnt/β‐catenin signaling also regulated the HR and FA pathway." (PMID 33660437, 2021). "APC gene mutations are known to be associated with chromosomal instability, however, similar to our findings several studies have identified that mutated APC was associated with improved survival as compared to wild-type APC in colorectal cancer." (PMID 34204917, 2021). "Indeed, at least 96% of colorectal cancers have aberrant WNT signaling as a consequence of genomic alterations in the APC or CTNNB1 (gene encoding β-catenin) locus." (PMID 33557356, 2021). "Indeed, the Wnt/β-catenin pathway is constitutively active in most colorectal cancers, where the loss of function mutation and/or epigenetic silencing of negative regulators like APC, AXIN2, DKK1, or SFRP2 are common facts." (PMID 34063173, 2021). "Mutation rates of APC in colorectal cancer can reach 80%6–8." (PMID 34155197, 2021). "Somatic MUTYH mutations have been described in sporadic colorectal cancer and may occur concurrent to somatic adenomatous polyposis coli (APC) gene mutations." (PMID 33419231, 2021). "In addition, we designed pegRNA/PE3-guide pairs to generate mutations in APC, the gene that is often the first to be mutated in colorectal cancer." (PMID 34373320, 2021). "Deleterious mutations in APC gene cause the autosomal dominant familial adenomatous polyposis (FAP) which is typically characterized by the occurrence of hundreds to thousands of colorectal adenomas that eventually lead to colorectal cancers (CRCs)." (PMID 33842374, 2021). "In human cancer, APC gene mutation was first revealed in colon cancer and colorectal cancer." (PMID 32486158, 2020).
colorectal cancer (continued). "The tumor suppressor adenomatous polyposis coli (APC) is frequently mutated in colorectal cancers." (PMID 33060621, 2020). "Moreover, restoration of APC activity has also shown a potential benefit in patients with inherited colorectal cancer carrying nonsense mutations that lead to premature stop codons." (PMID 33348689, 2020). "Ephb6 with APC mutation is found to be overexpressed in colorectal cancer." (PMID 32993565, 2020). "In addition to colorectal cancer, APC mutations are found in familial adenomatous polyposis (FAP), pancreatic, gastric, liver, stomach, thyroid, and skin cancers." (PMID 32486158, 2020). "Wnt pathway is activated abnormally in CRCs that occur sporadicallyand moreover, 90% of colorectal cancers and caused because of the functional loss of adenomatous polyposis coli (APC) tumor suppressor gene, which result in the constitutive activationof Wnt signaling." (PMID 32831519, 2020). "Finally, APC mutations in colorectal cancer, KRAS in gastric cancer, and pancreatic cancer were mostly associated gene alterations." (PMID 33127962, 2020). "Therefore, we conclude that the co-mutation of BRAF and APC in colorectal cancers is conducive to an aggressive phenotype." (PMID 32384699, 2020). "Further investigation was undertaken to determine whether loss of heterozygosity and/or methylation of the APC gene promoter region may have contributed to silencing of the second APC gene allele in these early-onset colorectal cancers." (PMID 33352971, 2020). "APC mutations drive human colorectal cancer (CRC) development." (PMID 33112876, 2020). "APC mutations occur in 42% of colorectal cancer and 14% of small bowel cancer." (PMID 31729414, 2019). "Considering the high frequency of mutated APC in patients with colorectal cancer, further studies are needed to investigate APC’s molecular mechanism in β-catenin degradation, its use as a potential biomarker and other possible therapeutic targeting approaches." (PMID 31382613, 2019). "Upregulation of Dvl sustains Wnt/β-catenin signaling, whereas Dvl2 loss suppresses tumor development in the intestine of the APC-mutant mouse, suggesting Dvl2 may represent a potential target for colorectal cancer therapy." (PMID 30866999, 2019). "Unsurprisingly, given its importance in gut development, maintenance and homeostasis, deregulation of Wnt signalling is an initiating factor in colorectal tumorigenesis; with adenomatous polyposis coli (APC) mutation being the most frequent event in colorectal cancers (CRCs)." (PMID 30792270, 2019). "The prevalence of APC mutations in colorectal cancers suggest APC as a powerful target for therapy." (PMID 31382613, 2019). "The synergy between TNKS and CDK4 inhibition was not restricted to DLD1 cells, as we observed similar effects of TNKS silencing and Trametinib or Palbociclib treatment in the colorectal carcinoma cell line SW480 (bearing an APC truncating mutation, similar to DLD1)." (PMID 31891587, 2019). "Our observation revealed that β-catenin may have a vital part in the progression of colorectal carcinoma and that activating mutation of the β-catenin gene may substitute bi-allelic APC inactivation in this tumor type in Pakistani Population." (PMID 31699039, 2019). "The mutation in APC may lead to a series of cancers such as ovarian cancers, medulloblastomas, pilomatrixomas, and colorectal cancers." (PMID 29369179, 2018). "Whereas a select few assays, for example, APC or KRAS mutations in colorectal cancer, BRAF in melanoma encompass a significant proportion of patients, and are thus reliable aberrations to use a surrogate for tumour fraction, the equivalent targets have yet to be demonstrated in MIBC." (PMID 30158468, 2018).
colorectal cancer (continued). "Since β-catenin phosphorylation in colorectal cancer cells is impaired due to APC truncations or impossible due to β-catenin mutations, it is unlikely that increased GSK3 activity can be accounted for inhibition of Wnt/β-catenin signaling by SFN in SW480, DLD1 and HCT116 cells." (PMID 30338040, 2018). "Somatic mutations occur at the level of the APC in the large majority of colorectal cancers, while germ-line mutations of the APC gene occur in the FAP, characterized by the formation of a very large number of polyps in the colorectum, with a high risk of cancer transformation of these adenomas." (PMID 29652830, 2018). "Interestingly however, evidence for selection of APC mutations above CTNNB1 mutations was found in colorectal cancer only." (PMID 29748584, 2018). "In breast cancer, co-expression of Wnt ligands, including Wnt3, Wnt4, Wnt5a, and Wnt7a, leads to the activation of Wnt pathway, while in colorectal cancer, mutation or loss function of the APC gene or protein is more likely to be the reason for Wnt pathway activation." (PMID 29986466, 2018). "Biallelic APC mutations initiate the development of a high percentage of colorectal cancers." (PMID 30131849, 2018). "Loss of APC function by this variant has been suggested to activate Wnt signaling in colorectal cancer and hepatocellular carcinoma, but this is unknown in HB." (PMID 30619485, 2018). "Future therapeutic strategies for APC-deficient colorectal cancers might be expanded to include agents targeting the AP-1 pathway." (PMID 30131849, 2018). "This pathway is thought to be distinct from the conventional adenoma-carcinoma pathway, where adenomas progress to invasive colorectal carcinomas through the influence of several genetic alterations including adenomatous polyposis coli (APC) and KRAS mutations." (PMID 30458818, 2018). "Adenomatous polyposis coli (APC) mutation was found in early stage colorectal cancer, invisible chromosome familial adenomatous polyposis and most sporadic colorectal cancers, and might lead to its occurrence and development." (PMID 28851367, 2017). "In addition to APC mutations in colorectal cancers, WNT signaling can also be aberrantly activated via mutations that stabilize β-catenin or impaired AXIN1/2 function, although these are less ubiquitously found." (PMID 28587062, 2017). "It would be interesting to see whether SRI37892 can indeed effectively inhibit Wnt/β-catenin signaling in colorectal cancer cells harboring APC and CTNNB1 mutations." (PMID 29207657, 2017). "Notably, the p.I1307K missense mutation in APC (rs1801155), which has been previously shown to moderately increase colorectal cancer risk in the AJP, was among the identified variants (MAF = 0·047), and was recommended for inclusion in AJP screening." (PMID 28502252, 2017). "Diverse mechanisms may induce this event in colorectal carcinoma, the major cause being dysfunction of the APC gene." (PMID 28824332, 2017). "In addition, mutations in β-catenin (CTNNB1) and APC have been identified in sporadic colorectal cancers and various other tumor types." (PMID 27898031, 2016). "Accordingly, a recent study identified a novel somatic insertion in the APC gene and a hot spot for L1 insertion on Chromosome 17, suggesting that the L1 insertion initiates colorectal cancer (CRC) by mutating the APC gene through the classic two-hit CRC pathway." (PMID 27446907, 2016).
colorectal cancer (continued). "Over 94% of colorectal cancer cells have mutations in one or more members of the Wnt signaling pathway, of which 80% of sporadic colorectal cancers are associated with mutation of APC and 10% with mutation of CTNNB1, the gene encoding the protein of β-catenin." (PMID 26862734, 2016). "Mutation of APC was shown to be associated with the emergence of colorectal cancer." (PMID 26862903, 2016). "APC mutations are a major contributing factor to colorectal cancer." (PMID 27028212, 2016). "Previous studies have addressed the association between SNPs in APC and colorectal cancer risk." (PMID 27028212, 2016). "Approximately 85% colorectal cancer reported with APC protein mutation." (PMID 26760960, 2016). "Our results indicate that many SNPs in APC promoters 1A and 1B are functionally relevant and that allele G of rs79896135 may be associated with the predisposition to colorectal cancer." (PMID 28105931, 2016). "In addition, to simulate tumor development of colorectal cancer associated with APC mutation and determine the inhibitory effect of n-3 PUFAs in vitro, we constructed a new study model by transfecting the normal colon cell line NCM460 with APC siRNA." (PMID 27769066, 2016). "The APC gene, located at chromosome 5q21–5q22, was originally implicated in colorectal cancer." (PMID 27478702, 2016). "Somatic mutations of APC occur early in the development of a sporadic colorectal carcinoma." (PMID 26970738, 2016). "APC mutations which are characteristic of colorectal cancer were only found in two patients." (PMID 26315110, 2015). "However, APC mutation or dysregulation of Wnt ligands results in loss of β-catenin degradation in colorectal cancer cells." (PMID 26317652, 2015). "Mutations in the APC gene could be found in 81% of colorectal cancer cell lines, indicating the critical role of APC in CRC tumorigenesis." (PMID 25617745, 2015). "For example, Wnt is active in 90% of the patients with colorectal cancer due to mutations in APC and β-catenin genes, but mutations in these genes are rare in HCC patients despite the fact of existence of the canonical Wnt signal resulting in cytosolic and nuclear accumulation of β-catenin in HCC." (PMID 25896897, 2015). "Of the 10 patients with cancers other than colorectal and FBXW7 mutations, none (0%) had simultaneous KRAS mutations or APC mutations compared to 6/7 (86%) patients with KRAS mutations and 3/7 (43%) with APC mutations in the colorectal cancer group (p = 0.0006 and p = 0.022)." (PMID 24586741, 2014). "Somatic APC mutations are found in the majority of sporadic colorectal cancers." (PMID 24790607, 2014). "The loss of function of the APC gene mutation is the most common mutation in colorectal cancer." (PMID 25713610, 2014). "More than 80% of colorectal cancer (CRC) is associated with the APC mutation." (PMID 25211188, 2014). "DLD1 cells are also a colorectal cancer cell line with another APC mutation." (PMID 25121615, 2014). "SW480 cells are a colorectal cancer cell line with a mutated adenomatous polyposis coli (APC) gene." (PMID 25121615, 2014).
colorectal cancer (continued). "Indeed, a great amount of experimental evidence has shown that mutations in the adenomatous polyposis coli (APC) gene act as gatekeepers in the molecular pathogenesis of the majority of sporadic and hereditary forms of colorectal carcinoma." (PMID 25396735, 2014). "APC is a well-known target during the early stages of colon cancer: truncation of the APC protein occurs in >80% of colorectal cancers (CRC) and it is associated with the initial stages of oncogenic transformation, which suggests a functional role for our newly identified splicing variant." (PMID 24498620, 2013). "Although APC loss is considered an initiating event in colorectal cancer, for example, it is less clear what role APC plays in tumor cell motility and whether loss of APC might be an important promoter of tumor progression in addition to initiation." (PMID 23302090, 2013). "These could comprise loss of both maternal and paternal APC alleles in the numerically dominant colorectal cancer pathway." (PMID 24195059, 2013). "Allele-specific RNA interference of APC allows in principle to envisage a patient-specific therapy for colorectal cancer, whereby only cells affected by a mutation in the APC gene will be hampered in their proliferation capacity upon acquisition of a shRNA matching the mutation." (PMID 22509309, 2012). "The intense nuclear signal commonly observed in colorectal tumors may reflect a specific response to APC mutation, the causal event in the majority of human colorectal cancers." (PMID 22457761, 2012). "Interestingly, two common APC inactivating mutations (APC-R405X and APC-R283X), both frequent mutations in colorectal cancer, are present at different prevalence (25% and 49%, respectively), suggesting that they occur in different cell populations." (PMID 22185227, 2011). "Aneuploidy in these tumours may be driven by chromosomal instability (CIN), which is common in colorectal cancers initiated by APC mutation and may result from defects in chromosomal segregation during mitosis." (PMID 22216133, 2011). "Colorectal cancer progression begins with mutations in the Small GTPase pathway, followed by alterations of the Apoptosis/Wnt-Notch and Homophilic cell adhesion pathways, often caused by a single APC mutation." (PMID 22069497, 2011). "Mutations in the adenomatous polyposis coli (APC) gene are found in most colorectal cancers." (PMID 21857949, 2011). "Certain APC mutations may be common in colorectal cancer because they enhance stem cell survival during niche clonal evolution and shorten pathways by effectively increasing subsequent numbers of stem cells at risk." (PMID 20051132, 2010). "In this way, certain APC mutations may be more common in colorectal cancers because when acquired earlier in life, they also favor persistence of its stem cell through subsequent crypt clonal evolution cycles." (PMID 20051132, 2010). "Transformation of a stem cell lineage later in life is contingent on its persistence earlier in life despite periodic threats of extinction during niche clonal evolution, which may help explain why APC mutations are found in nearly all colorectal cancers." (PMID 20051132, 2010). "In the case of colorectal cancer, loss of APC and activation of KRAS are common." (PMID 20298593, 2010). "Familial adenomatous polyposis, an autosomal dominant inherited disease caused by germline mutations within the APC gene, is characterized by early onset colorectal cancer as a consequence of the intrinsic phenotypic feature of multiple colorectal adenomatic polyps." (PMID 20649969, 2010). "Somatic mutations of the APC gene cause malfunctioning APC in 80% of colorectal cancers." (PMID 20029639, 2009). "Furthermore, LPA receptors have been shown to increase cell proliferation in APC-mutated colorectal cancer cells by inhibiting β-catenin degradation via Wnt signaling modulation lines." (PMID 19238201, 2009).